MTOR (mechanistic target of rapamycin kinase)
Diseases named in the same sentence as MTOR in open-access papers (continued):
Sharing a sentence is not in itself a finding about the gene and the disease.
breast cancer (continued). "Accordingly, this work was designated to impregnate MSC conditioned media with a common PI3K/Akt/mTOR inhibitor, Wortmannin, to explore their combined antiproliferative effect against luminal-A breast cancer cells and to monitor their impact on PI3l/mTOR pathway." (PMID 40038752, 2025). "Given the well-established role of the PI3K/AKT/mTOR signaling axis in promoting oncogenic phenotypes in breast cancer, we hypothesized that miRNA-195-5p might exert its tumor-suppressive functions by modulating this pathway." (PMID 41141380, 2025). "Notably, hyperactivation of Akt1 has been observed in approximately half of breast cancers, often attributed to mutations or amplifications within the PI3K/Akt/mTOR axis." (PMID 40798865, 2025). "Resistance mutations that reactivate the PI3K/AKT/mTOR pathway occur in the context of PI3Kα inhibition, e.g., loss of PTEN/AKT activation in breast cancer patients treated with alpelisib or inavolisib, as well as further mutations in PI3Kα itself at progression." (PMID 40360883, 2025). "Additionally, previous studies have determined that there is a compensatory increase in activation of the HER2/ERK signaling pathway in response to PI3K/Akt/mTOR inhibition in the treatment of breast cancer." (PMID 40943615, 2025). "For example, in the case of HER2-positive breast cancer, resistance to HER2-targeted therapies, such as trastuzumab, can occur through mutations in the HER2 receptor or the activation of alternative pathways like the PI3K/Akt/mTOR signaling cascade." (PMID 40277781, 2025). "Additionally, Canagliflozin has been shown to upregulate BRCA1 while suppressing mTOR‐mediated inflammatory and pyroptotic signaling, reinforcing its therapeutic potential in breast cancer management." (PMID 41523619, 2025). "Furthermore, blocking PI3K signaling by alpelisib or inavolisib reduced SREBP1 and SCD-1 expression, suggesting that HER2/PI3K/AKT/mTOR signaling regulated the de novo lipogenesis machinery in HER2-positive breast cancer cells." (PMID 39920872, 2025). "Additionally, three candidate genes are associated with Breast cancer (DLL3, BRCA2, WNT2B), the mTOR signaling pathway (WNT2B, TELO2, TNFRSF1A), and Pathways in cancer (DLL3, BRCA2, WNT2B)." (PMID 40919429, 2025). "For example, biejia extract could inhibit PI3K/Akt/mTOR signaling in MDA-MB-231 breast cancer cells, attenuating EMT and metastatic behaviors." (PMID 40620671, 2025). "Interestingly, the polyamine pathway has been found to interact with the PI3K/AKT/mTOR pathway in breast cancer cells." (PMID 40299687, 2025). "Therefore, AKT inhibitors represent a promising avenue for cancer therapy, particularly in breast cancer where the PI3K/AKT/mTOR pathway is frequently dysregulated." (PMID 38255807, 2024). "Moreover, CCL3 plays a vital role in promoting EMT via the PI3K-protein kinase B (Akt)-mTOR signaling pathway in breast cancer cells when co-cultured with myeloid-derived suppressor cells." (PMID 39684816, 2024). "The PI3K/AKT/mTOR pathway is the target through which miR-1297 also promotes breast cancer." (PMID 38338777, 2024). "Finally, MERIT40 is a downstream effector of the Pi3k/Akt/mTOR pathway that complexes with breast cancer gene, (BRCA)-1 in response to DNA damage to promote DNA repair, chemotherapeutic resistance, and the survival of malignant cells." (PMID 38263212, 2024). "PI3K/Akt/mTOR signalling is a key regulator of cellular events such as growth, proliferation, survival and invasiveness in cancers, and has become an attractive target in the therapy of breast cancer." (PMID 39084065, 2024).
breast cancer (continued). "For instance, the H1047R mutation in the oncogenic PIK3CA gene in breast cancer enhances PI3K enzyme activity, activating the AKT/mTOR signalling pathway and inducing the glycosylation of membrane metalloendopeptidase, ultimately resulting in tumour cell senescence." (PMID 39270064, 2024). "Exploring novel combinations of PI3K/AKT/mTOR inhibitors may offer a new perspective on breast cancer management, particularly for cases exhibiting resistance to endocrine therapy and a higher risk of recurrence." (PMID 39448637, 2024). "For instance, BCAT1, by enhancing mitochondrial biosynthesis and function through mTOR mediation, may stimulate breast cancer cell growth." (PMID 38309289, 2024). "Although the mTOR pathway seems to be related to Ca2+ mobilization, this relationship is not fully understood, and the association between Ca2+ and and AKT signaling is still unclear in breast cancer cells." (PMID 39001475, 2024). "In order to provide additional evidence of the inhibitory effects of formononetin on breast cancer proliferation through its impact on mTORC1 activity, we conducted a co-administration study using Formononetin and the mTOR inhibitor Torin-1 on MDA-MB-231 and MDA-MB-468 cells." (PMID 39399463, 2024). "CBD was also found to facilitate a PPAR-mediated apoptotic pathway in MDA-MB-231 cells and ER+ T-47D cells; the study by Sultan and co-workers demonstrated the upregulation of the transcription factor PPARy in breast cancer cell lines accompanied by the downregulation of mTOR and cyclin D1." (PMID 38891847, 2024). "mTOR has been reported to be dysregulated in approximately 70% of breast cancers." (PMID 38892329, 2024). "Moreover, natural substances such as magnoflorine have been shown to enhance Dox sensitivity by blocking the PI3K/AKT/mTOR pathway, thereby inducing autophagy and promoting cell death in breast cancer cells." (PMID 39199310, 2024). "miRNA-10a suppresses breast cancer progression via the PI3K/Akt/mTOR pathway." (PMID 39769169, 2024). "Additionally, hypoxia inhibits protein synthesis through a pathway involving eukaryotic translation initiation factor 4E-binding protein 1 (4E-BP1) and elongation factor 2 kinase, controlled by mTOR and uncoupled in breast cancer cells." (PMID 39494346, 2024). "Higher expression of ADRA2A was also associated with breast cancer survival and hypothesized to suppress cell proliferation and invasion through the PI3K/AKT/MTOR pathway in cervical cancer." (PMID 38664626, 2024). "Activation of the PI3K/AKT/mTOR signaling pathway, whether due to mutations in pathway components or activation of upstream signaling molecules, is common in HER2-positive breast cancer." (PMID 38542136, 2024). "This suggests that the Rg3–NIR group may be able to reverse MCF‐7/ADR resistance and breast cancer progression by inhibiting the PI3K/AKT/mTOR signaling pathway." (PMID 39139957, 2024). "Furthermore, co-culture of CD3+T-cells with B7-H3+ breast cancer cells resulted in IFN-γ downregulation through decreased PI3K/AKT/mTOR signaling." (PMID 38250867, 2024). "In addition to collagen and PIK3 pathway genes, qRT-PCR results also confirmed the upregulation of MAPK and mTOR signaling pathway genes across all breast cancer subtypes." (PMID 39850811, 2024). "Western blot analysis was performed for p-AKT (Ser473), p-AKT1S1 (Thr246), and p-mTOR (Ser2448) in the HR+ breast cancer cell lines MCF-7, ZR-75, and MCF-7-Y537S following exposure to 10 dyn/cm2 of FSS using the microfluidic device followed by seeding in culture and growth on TCP." (PMID 39000231, 2024). "Additionally, the mTOR signaling pathway, another cancer-related pathway, is found to be shared between breast cancer and high LDL." (PMID 38947022, 2024). "In addition, previous studies have indicated that PI3K/mTOR inhibitors can synergise with PD‐1 blockade in syngeneic mouse models of melanoma, prostate, colorectal and breast cancer." (PMID 38711203, 2024).
breast cancer (continued). "Furthermore, it was also found that the combination of doxorubicin (DOX) and magnoflorine (Mag) inhibited the proliferation and migration of breast cancer, acting by suppressing autophagy induced by mTOR-dependent signaling pathway." (PMID 38315272, 2024). "Therefore, hyperactivation of mTOR is crucial in the development of invasive breast cancer; an anti-breast cancer effect can be produced by cell cycle arrest that induces mTOR-specific siRNA through apoptosis." (PMID 39335585, 2024). "Zinc finger protein CXXC5 promotes breast cancer by regulating TSC1/mTOR signaling pathway." (PMID 39717098, 2024). "Specifically, the identification of miRNAs such as miR-129, miR-19a-3p, and miR-30d-5p, as well as proteins like COL4A1, MAPK3, PIK3CG, and mTOR, provides valuable insights into the molecular mechanisms underpinning aggressive breast cancer subtypes, such as TNBC." (PMID 39850811, 2024). "Therefore, this study aimed to assess the expression profile of mRNA and miRNA related to the PI3K/AKT/mTOR signaling cascade in five types of breast cancer in Polish women." (PMID 39850811, 2024). "Although multiple compounds have been developed, at present, there are just three inhibitors approved to target this pathway in patients with advanced ER-positive, HER2-negative breast cancer: everolimus (mTOR inhibitor), alpelisib (PIK3CA inhibitor), and capivasertib (AKT inhibitor)." (PMID 38927964, 2024). "Treatments for certain diseases, including pancreatic neuroendocrine tumors, renal cell carcinoma, and breast cancer, involve the use of mTOR inhibitors, which may also improve the effectiveness of other cancer treatments." (PMID 39199310, 2024). "Activation of the PI3K/AKT/mTOR pathway in breast cancer has been reported to induce cell proliferation, and in this research, the increased proliferation might result from the induced PI3K/AKT/mTOR pathway." (PMID 38225865, 2024). "Furthermore, rapamycin (ABI-009) is being considered for use as an anti-cancer drug targeting the mTOR signal in breast cancer stem cells." (PMID 39349424, 2024). "The majority of patients with ER-positive, HER2-negative advanced breast cancer will likely be offered an inhibitor of the PI3K/AKT/mTOR pathway at some point in their cancer journey, with the options available depending on the approval criteria in place and the cancer's mutation status." (PMID 38927964, 2024). "Additionally, co-treatment of everolimus (RAD001) with the anti-estrogen drug exemestane (FCE-24304) for hormone receptor-positive breast cancer therapy showed alleviation of breast cancer by inactivating the mTOR signal in patients." (PMID 39349424, 2024). "Therefore, it can be concluded that the Rg3–NIR inhibits breast cancer progression by targeting the PI3K/AKT/mTOR pathway." (PMID 39139957, 2024). "mTOR inhibitors exert potential antitumour effects against certain subtypes of breast cancer." (PMID 38734930, 2024). "Many breast cancer therapeutics target the PI3K/AKT/mTOR oncogenic pathway." (PMID 39749216, 2024). "To investigate whether RPN1 functions in breast cancer pathogenesis through the activation of PI3K/AKT/mTOR signaling, we analyzed the impact of RPN1 on PI3K/AKT/mTOR signaling pathway activation." (PMID 38302629, 2024). "Collectively, these preclinical studies suggest that dual pathway targeting by vepdegestrant and CDK4/6 or PI3K/mTOR signaling could result in better therapeutic outcomes for patients with advanced ER+/HER2− breast cancer." (PMID 39767607, 2024). "One mechanism may be in the increased phosphorylation of p-mTOR in HR+ breast cancer cells following exposure to FSS." (PMID 39000231, 2024).
breast cancer (continued). "Dysregulation of the PI3K/AKT/mTOR pathway by activating mutations in PIK3CA and AKT1 and/or inactivating PTEN are most frequently observed in HR+/HER2- BCs, which are found to be mutually exclusive (GENIE breast cancer cohort)." (PMID 39796647, 2024). "Reportedly, OGN could inhibit the capacity of tumor cells to proliferate and invade through the PI3K/Akt/mTOR signaling in breast carcinoma." (PMID 38402185, 2024). "Regarding this hypothesis, we have shown that metformin failed to suppress basal tumor growth in 4T1-bearing mice, but suppressed both growth and phosphorylated-mTOR/S6K levels in 4T1 mammary tumors, but only when co-administered with a DPP-4 inhibitor." (PMID 37760498, 2023). "The PI3K/Akt/mTOR pathway is necessary for the regulation of proliferation, protein synthesis, apoptosis, cell motility and angiogenesis and is dysregulated in several canine mammary tumors." (PMID 37835752, 2023). "Additionally, metformin activates adenosine monophosphate-activated protein kinase (AMPK), decreases the mammalian target of rapamycin (mTOR) and S6 kinase activation, and decreases mRNA translation in breast cancer." (PMID 37370809, 2023). "Therefore, scientometric techniques and visualization tools were employed to analyze the large number of bibliographic metadata related to the research area of mTOR and breast cancer." (PMID 37637052, 2023). "Among other signals, PIEZO1 activates Akt/mTOR (mammalian target of rapamycin) pathway in breast cancer, and may subsequently positively regulate cell motility and survival." (PMID 37490147, 2023). "It was showed that gallic acid effectively against metastasis in various cancer cell types such as myeloid leukemia, breast cancer and ovarian cancer by modulating multiple signalling pathways, including Akt/mTOR, ERK, MMPs, NFκB, PTEN/Akt/HIF-1α/VEGF pathways." (PMID 37957642, 2023). "In this study, we found that IC2 could induce cytoprotective autophagy in breast cancer cells via the AMPK/mTOR- and MAPK-signaling pathways." (PMID 36770781, 2023). "Therefore, the mTOR inhibitor everolimus in combination with endocrine therapy has become a therapeutic option for HR+ advanced breast cancer (ABC) upon disease progression after first‐line anti‐hormonal therapies with or without CDK4/6 inhibitors." (PMID 36263515, 2023). "The CXCR4 inhibitor treatment decreased the KR-induced gene expression profile and breast cancer progression when compared to that of the KR alone group, suggesting that mTOR pathway activation is relevant for DPP-4 inhibitor-mediated breast cancer progression." (PMID 37760498, 2023). "The enrichment results were focused on human disease-related pathways, including breast cancer, non-small cell lung cancer, pancreatic cancer, mammalian target of rapamycin (mTOR), vascular endothelial growth factor (VEGF), and forkhead box proteins of the class O subgroup (FoxO) signaling pathway." (PMID 37107564, 2023). "Further, RA-induced apoptosis in breast cancer cells is mediated by the PI3K/AKT/mTOR pathway." (PMID 36726491, 2023). "Moreover, PI3K/Akt/mTOR can induce the phosphorylation of c-Jun that is part of the AP-1 complex that contributes to ERα activity, breast cancer progression, invasiveness, and tamoxifen resistance." (PMID 37172090, 2023). "Furthermore, dysfunction of the mTOR pathway participates in breast cancer tumorigenesis and the mechanism of resistance to endocrine therapy." (PMID 36539038, 2023). "Therefore, a scientometric analysis was conducted on articles related to mTOR in breast cancer to outline the current state of research." (PMID 37637052, 2023). "mTOR signaling was studied in the development of breast cancer and resistance to targeted therapy." (PMID 38046946, 2023). "HIF-1α is also a downstream target of mTOR in breast cancer cells." (PMID 37760498, 2023). "Top 10 authors who have contributed to the study of mTOR and breast cancer." (PMID 37637052, 2023).
breast cancer (continued). "We found that PRS could promote apoptosis of 4T1 tumor cells via the AKT/mTOR pathway, inhibiting breast cancer growth." (PMID 37896137, 2023). "Here, we show that MYC activation drives resistance to mTOR inhibitors (mTORi) in breast cancer." (PMID 37642941, 2023). "Additionally, FAM83D can also regulate EMT through Akt/mTOR and promote the development of lung and breast cancer." (PMID 35796646, 2023). "Mechanistic studies also indicated that GARS may act as an oncogene in breast cancer through controlling the mTOR pathway and regulating cellular proliferation." (PMID 36901698, 2023). "In addition, in breast cancer cell lines and primary tumors, the mammalian target of rapamycin (mTOR), a master regulator of metabolism that balances anabolism and catabolism, is targeted by FBXW7 for ubiquitination and degradation." (PMID 37176148, 2023). "Recent studies have indicated that mTOR plays a critical role in maintaining stemness-related functions in cancer stem cells (CSCs), and the inhibition of mTOR leads to the sensitization of CSCs to radiation therapy in breast cancer." (PMID 37631344, 2023). "Consequently, combined mTOR and endocrine blockage demonstrated synergistic effects in a preclinical breast cancer model." (PMID 37623437, 2023). "Moreover, in breast cancer, PI3K/Akt/mTOR pathway activation is one of the main causes of resistance to antitumor therapies and thus is an important target for improving the sensitivity of tumors to antitumor therapies." (PMID 36979714, 2023). "Curcumin also suppressed protein kinase B (Akt)/mammalian target of rapamycin (mTOR) phosphorylation, decreased B-cell lymphoma 2 (BCL2), and enhanced BCL-2-associated X protein (BAX) and caspase 3 cleavage, resulting in apoptosis in breast cancer cells." (PMID 36836717, 2023). "Regarding the pleiotropic effects of DPP-4 inhibitors on cancer biology, we have previously shown that DPP-4 suppression accelerates breast cancer metastasis by inducing EMT through C-X-C motif chemokine 12 (CXCL12)/C-X-C receptor 4 (CXCR4)-mediated mTOR activation." (PMID 37760498, 2023). "To confirm whether ASR-600 affects other pro-survival signaling pathways apart from AR in CRPC, we examined AKT, mTOR, Estrogen receptor (ER), and Progesterone receptor (PR) expressions in prostate and breast cancer cell lines." (PMID 36937838, 2023). "SNORA38B was reported to have a potential role in the PI3K-AKT/ERK/mTOR pathway in breast cancer." (PMID 37686617, 2023). "Since Akt can activate mTOR signaling which drives tumor progression, several allosteric and ATP-competitive Akt inhibitors are under development, with only MK-2206 further investigated in breast cancer." (PMID 37662839, 2023). "Here, we review the role of the PI3K/AKT/mTOR pathway in ER+ advanced breast cancer, highlighting the genomic contexts in which the various inhibitors of this pathway may have superior activity." (PMID 36901954, 2023). "The PI3K/Akt/mTOR pathway is dysfunctional in many tumors, promoting the biological processes of proliferation, invasion and evasion of cell death, but drug resistance in breast cancer." (PMID 37662839, 2023). "Further investigations aimed at unraveling the coordination between O-GlcNAcylation and the mTOR pathway, particularly at the structural level, could offer insights into the mechanism governing the development of palbociclib resistance in breast cancer cells." (PMID 37886470, 2023). "Both IGF-1R/PI3K/AKT/mTOR and Hippo pathways are crucial for breast cancer stem cells (BCSCs)." (PMID 37081542, 2023). "In this regard, LACTB was shown to mediate tumour suppression through PI3K/AKT/mTOR in colorectal cancer, inhibiting Hippo pathway in melanoma, modulating lipid metabolism in breast cancer and hepatocellular carcinoma and regulating autophagy in gastric cancer." (PMID 36282364, 2023).